TLR7 (toll like receptor 7)
Description:
Endosomal receptor that plays a key role in innate and adaptive immunity. Controls host immune response against pathogens through recognition of uridine-containing single strand RNAs (ssRNAs) of viral origin or guanosine analogs. Upon binding to agonists, undergoes dimerization that brings TIR domains from the two molecules into direct contact, leading to the recruitment of TIR-containing downstream adapter MYD88 through homotypic interaction. In turn, the Myddosome signaling complex is formed involving IRAK4, IRAK1, TRAF6, TRAF3 leading to activation of downstream transcription factors NF-kappa-B and IRF7 to induce pro-inflammatory cytokines and interferons, respectively. In plasmacytoid dendritic cells, RNASET2 endonuclease cooperates with PLD3 or PLD4 5'->3' exonucleases to process RNA and release 2',3'-cyclic guanosine monophosphate (2',3'-cGMP) and cytidine-rich RNA fragments that occupy TLR7 ligand-binding pockets and trigger a signaling-competent state.
Synonyms: IMD74; SLEB17; TLR7-like
Tractability: Small molecule: an approved drug acts on it; a high-quality ligand is known; it belongs to a druggable protein family. Antibody: its Gene Ontology location is reachable by antibodies, with high confidence; UniProt predicts a signal peptide or a membrane-spanning region. PROTAC: ubiquitination databases record sites on it; its protein half-life has been measured; a small molecule that binds it is known. Other modalities: a drug acting on it is in phase 2 or 3 trials.
Target class: Toll-like and Il-1 receptors; Membrane receptor
Chemical probes: ENPATORAN, PD064720, SM 324405
Gene: Protein-coding gene on chromosome X (12,867,072 to 12,890,361, forward strand). Ensembl gene ENSG00000196664.
Subcellular location: Endoplasmic reticulum membrane; Endosome; Lysosome; Cytoplasmic vesicle, phagosome
Pathways (Reactome):
Immune System: MyD88 dependent cascade initiated on endosome; Regulation of TLR by endogenous ligand; TRAF6 mediated IRF7 activation in TLR7/8 or 9 signaling; TRAF6 mediated induction of NFkB and MAP kinases upon TLR7/8 or 9 activation; Toll Like Receptor 7/8 (TLR7/8) Cascade; Trafficking and processing of endosomal TLR
Disease: Defective regulation of TLR7 by endogenous ligand; Potential therapeutics for SARS; RSV-host interactions; SARS-CoV-1 activates/modulates innate immune responses; SARS-CoV-2 activates/modulates innate and adaptive immune responses
Gene Ontology:
Molecular function: double-stranded RNA binding; pattern recognition receptor activity; protein binding; single-stranded RNA binding; siRNA binding
Biological process: canonical NF-kappaB signal transduction; cellular response to mechanical stimulus; defense response to virus; innate immune response; positive regulation of canonical NF-kappaB signal transduction; positive regulation of chemokine production; positive regulation of inflammatory response; positive regulation of interferon-alpha production; positive regulation of interferon-beta production; positive regulation of interleukin-8 production; positive regulation of type II interferon production; response to cGMP; toll-like receptor 7 signaling pathway; positive regulation of interleukin-6 production; toll-like receptor signaling pathway; cellular response to virus; defense response; endolysosomal toll-like receptor signaling pathway; immune response; JNK cascade; MAPK cascade; positive regulation of transcription by RNA polymerase II; response to other organism; signal transduction; toll-like receptor 8 signaling pathway
Cellular component: cytoplasm; lysosomal membrane; plasma membrane; receptor complex; early phagosome; endolysosome membrane; endoplasmic reticulum; endoplasmic reticulum membrane; endosome; endosome membrane; Golgi membrane; lysosome; phagocytic vesicle
Gene-disease validity (ClinGen):
ClinGen rates the evidence that TLR7 causes each of these diseases.
systemic lupus erythematosus 17 (X-linked): Moderate. Any systemic lupus erythematosus in which the cause of the disease is a variation in the TLR7 gene.
Homologues: Orthologues: chimpanzee TLR7 (99% identical), macaque TLR7 (98% identical), dog TLR7 (86% identical), pig TLR7 (85% identical), guinea pig TLR7 (83% identical), mouse Tlr7 (81% identical), rat Tlr7 (81% identical), tropical clawed frog tlr7 (60% identical), zebrafish tlr7 (56% identical). Paralogues in human: TLR8 (42% identical), TLR3 (20% identical), TLR4 (17% identical), TLR2 (16% identical), TLR5 (16% identical), TLR1 (16% identical), LRRC32 (16% identical), TLR10 (15% identical), IGFALS (15% identical), CD180 (15% identical), NRROS (15% identical), TLR6 (15% identical), and 10 more.
Diseases named in the same sentence as TLR7 in open-access papers:
TLR7 is named in the same sentence as 463 diseases in open-access papers, as found by Europe PMC text mining. Sharing a sentence is not in itself a finding about the gene and the disease. The quoted sentences say what the papers report.
lupus (463 papers, 2008 to 2026). "The lupus-prone mouse strain, Y-linked autoimmune accelerator (Yaa), carries an extra copy of the TLR7 gene, leading to TLR7 hyperactivation." (PMID 40910948, 2026). "Among the genetic variants, certain alleles regulating the B cell activation pathway related with Toll-like receptor-7 (TLR7) have been associated with a higher risk of developing severe forms of lupus with early onset." (PMID 40761803, 2025). "For example, females appear to have a higher susceptibility to autoimmune diseases such as systemic lupus erythematosus, partly due to the higher expression and activation of TLR7 in B cells, which predisposes them to autoimmune conditions." (PMID 40143355, 2025). "Our study demonstrated that increased Cav2.2 protein expression in the spinal dorsal horn of lupus mice with chronic pain is associated with elevated TLR7 expression, and that activation of TLR7 with a TLR7 agonist in the normal spinal cord upregulates Cav2.2." (PMID 41511304, 2025). "An increased expansion and accumulation of M-MDSCs with active TLR7/IFN-α-mTOR signaling was found in a pristane-induced lupus mouse model, and it was associated with disease progression." (PMID 40725182, 2025). "In our lupus model mediated by TLR7-signaling, the deficiency in Bank1 gene particularly allowed an increase in the abundance of P. distasonis during lupus inflammation development and P. distasonis was proved to exert anti-inflammatory effects." (PMID 40761803, 2025). "PLD4 loss-of-function mutations in patients with systemic lupus erythematosus leads to excessive activation of TLR7 and TLR9." (PMID 40931063, 2025). "To determine if differences between signaling downstream of TLR779 and TLR777 affect disease severity in vivo, we assessed lupus-associated phenotypes in Tlr7+/+ Tlr9–/–, Tlr779/779 Tlr9–/– MRL/lpr mice." (PMID 40794441, 2025). "In 2022, gain-of-function (GOF) variants in TLR7 were first identified as a monogenic cause of systemic lupus erythematosus (SLE) in women." (PMID 40423910, 2025). "In parallel, the MNV infection of NCF190H mice upregulates Toll-like receptor 7 in macrophages, plasmacytoid dendritic cells and B220+ splenocytes, thereby promoting germinal center formation and lupus-associated autoantibodies production." (PMID 39939342, 2025). "Taken together, the NCF190H variant upregulates the MNV-induced TLR7 signaling pathway, to mediate activation of innate immune responses and lupus development." (PMID 39939342, 2025). "TLR7 activation has been implicated in the expansion of RNA-specific B cells in lupus-prone mice as well as monogenic lupus in humans." (PMID 39868594, 2025). "In the present study, we identify two new variants in UNC93B1 (T314A, located proximally to the TLR7 transmembrane domain, and V117L) in a cohort of east Asian patients with childhood-onset systemic lupus erythematosus." (PMID 38831104, 2024). "Rare genetic variants in UNC93B1 predispose to childhood-onset lupus via TLR7/-8–IRAK1/-4, validated with a corresponding mouse model." (PMID 38831104, 2024). "In both lupus models, mice deficient in Bank1 showed a significantly reduced proportion of IgG+ ABCs compared with TLR7.tg6 and IMQ-treated WT mice." (PMID 39163122, 2024). "An increased copy number of TLR7 causes SLE-like symptoms, and deletion of TLR7 attenuates symptoms, in lupus-prone mice." (PMID 38329126, 2024). "Genome-wide association studies have shown that polymorphisms in TLR7 are associated with lupus risk and cause more pronounced interferon signatures in humans." (PMID 38772735, 2024). "One likely endogenous source of TLR7 agonists and autoantigens that has been implicated in lupus and other autoinflammatory diseases are neutrophil extracellular traps (NETs)." (PMID 38346802, 2024). "High fat diet induced obesity aggravated the severity of lupus in TLR8 deficient female mice which develop spontaneous lupus-like disease due to increased TLR7 signaling by dendritic cells." (PMID 39639337, 2024).
lupus (continued). "TLR8 deficiency in mice results in lupus-like conditions, presumably mediated by the increased TLR7 expression." (PMID 39143032, 2024). "The effects of Bank1 deficiency on various lupus phenotypes in the TLR7.tg6 model, by 32 weeks of age, and the IMQ-induced model, by 20 weeks of age, were analyzed." (PMID 39163122, 2024). "A gain-of-function TLR7 variant that was identified in a child with severe lupus and then introduced into mice induced lupus-like features in a B cell–intrinsic manner independent of the formation of follicles or germinal centers." (PMID 39286970, 2024). "To investigate how ZEB2 impacts pathogenic ABCs, we investigated the consequences of Zeb2 deficiency in B cells using two lupus mouse models (lupus induced by the TLR7 agonist imiquimod (IMQ) and bm12 cell transfer) as well as an acute LCMV infection model." (PMID 38271512, 2024). "As for a D34A mutation causing murine lupus, we recorded a gain of TLR7 and, to a lesser extent, TLR8 activity with the I317M (in vitro) and G325C (in vitro and ex vivo) variants in the context of SLE." (PMID 38869500, 2024). "Global and B cell–intrinsic TLR7 deficiency rescues severe lupus in global Cybb-KO MRL.Faslpr SLE-prone mice." (PMID 39042716, 2024). "In vitro and in vivo studies demonstrated that S100A8/9 effectively promoted TLR7 pathway activation and that S100A8/9 deficiency reversed the promoting effect of MDSCs on TLR7 pathway activation in lupus." (PMID 38429401, 2024). "Extrafollicular ABCs and their plasma cell products, rather than GC-derived B cells, have been shown to drive the development of pathogenic B cell subsets in spontaneous TLR7-driven lupus models." (PMID 38701219, 2024). "TLR7 deficiency effectively alleviates the symptoms of lupus mice, while TLR7 overexpression triggers lupus-like autoimmune disease." (PMID 38429401, 2024). "TLR-7 gain-of-function mutations are recognized as a monogenic cause of human lupus, and hyperactive TLR-7 signaling is a known driver of autoimmune diseases in mouse models." (PMID 39337618, 2024). "At the same time, the overexpression of Tlr7 contributes to lupus phenotype in Yaa (Y-linked autoimmune acceleration) carrying mice, Tlr7 deficiency in Fcgr2b -deficient Yaa mice reduces plasma cell expansion and T cell activation." (PMID 38745067, 2024). "More recently, LoF variants in UNC93B1, which is important for endosomal transport and degradation of TLR7, has been reported to cause monogenic lupus." (PMID 38420886, 2024). "A missense mutation (p.Tyr264His) increasing TLR7 affinity for guanosine was carried by a female child suffering from severe lupus, and this dominant gain-of-function variant of TLR7 was sufficient to cause autoimmunity in both male and female transgenic mice." (PMID 37723501, 2023). "Despite the pathogenic role of TLR7, and despite that TLR7 and TLR9 are highly homologous and are thought to signal in similar ways, TLR9 plays a dominant protective role, while TLR7 is pathogenic in lupus." (PMID 37606042, 2023). "To this end, we created a floxed TLR7 allele directly on the lupus-prone MRL/lpr genetic background and used tissue-specific Cre-mediated deletion, along with BM chimera approaches, to define the CD11c+ cell– and B cell–specific roles of TLR7." (PMID 37606042, 2023). "Using wiskott-aldrich syndrome protein deficient (was-/-) chimeric mice with B cell specific TLR7 deletion similarly yielded reduced development of autoantibodies and progression of lupus-like glomerulonephritis." (PMID 37965337, 2023). "TLR7-deficient lupus mice show autoimmune inflammation remission, whereas TLR9-deficient lupus mice show a more severe autoimmune inflammation." (PMID 37872565, 2023). "It is known that pDCs potently produce type I IFNs in response to ligation of TLR7, which can be activated by RNA-containing ICs and are associated with B cell activation and lupus development." (PMID 36853827, 2023).
lupus (continued). "Overexpression of or gain of function in TLR7 is causal to the development of systemic lupus erythematosus (SLE) in humans and mouse models." (PMID 37733447, 2023). "Toll-like receptor 7 (TLR7)-deficient mice are protected from autoimmune diabetes and, in individuals with systemic lupus erythematosus, TLR7 can drive autoreactive naive B cells to differentiate into pathogenic plasma cell precursors." (PMID 36508037, 2023). "TLR7 overactivation is tightly linked to lupus pathogenesis, with a gain of function mutation resulting in a monogenic pediatric SLE and Tlr7 duplication in the Yaa locus or transgenic expression resulting in lupus phenotypes in mice." (PMID 37483626, 2023). "The ssRNA-sensing receptor TLR7 is implicated as a driver of lupus pathology in both murine models and human disease." (PMID 37606042, 2023). "To address this, we selectively deleted TLR7 in either CD11c+ cells or CD19+ cells; using a TLR7-floxed allele, we created on the lupus-prone MRL/lpr background, along with a BM chimera strategy." (PMID 37606042, 2023). "Age-associated B cells (ABCs), which are in part TLR7-polyclonal activated, are prominent in lupus and there is decreased thymic function with age." (PMID 36845162, 2023). "The duplicated Tlr7 gene in the Yaa and the resultant overexpression of TLR7 lead to lupus-like disease phenotypes, demonstrating the important role of TLR7-induced type I IFNs as the causative pathway for lupus." (PMID 36853827, 2023). "Introgression of TLR7 deficiency into genetic backgrounds predisposing to lupus conversely protected the mice against autoimmunity." (PMID 37723501, 2023). "There were a DC expansion and some signs of autoimmunity when Tlr7 was globally overexpressed in multicopy on the B6.Sle1 background (a lupus-prone strain harboring the Sle1 susceptibility locus)." (PMID 37606042, 2023). "TLR7 is a key determinant of the protective immunity, conversely, its dysregulation is linked to the susceptibility of inflammatory diseases, such as lupus, caused by activation of host-origin nucleic-sensing pathways via TLR7." (PMID 36677692, 2023). "Recent data show that the expression of TLR7 in mild and severe lupus-prone models is dependent on the activity of IRAK4 (the TLR7-downstream signaling molecule) and the pathogenic environment." (PMID 35309296, 2022). "TLR9-deficient mice have increased immune activation, accelerated lupus nephritis and mortality, whereas TLR7-deficient lupus-prone mice are protected from autoimmune disease; and renal disease was ameliorated as well." (PMID 36405752, 2022). "In lupus-prone TLR9-deficient mice the enhanced lupus disease is associated with functionally upregulated expression of TLR7 by B cells and pDCs, whereas the disease is suppressed upon TLR7 deletion." (PMID 36389822, 2022). "Constitutive TLR7 signaling is associated with the development of systemic lupus erythematosus–like autoimmune phenotypes in mice and humans." (PMID 35653193, 2022). "We report a novel model of lupus-associated cardiovascular pathology accelerated by the TLR7 agonist R848 in lupus-prone B6.Sle1.Sle2.Sle3 (TC) mice." (PMID 35860280, 2022). "In mice, increased TLR7 signalling due to the duplication of the TLR7-encoding Yaa locus or to transgenic TLR7 expression exacerbates autoimmunity and deletion of TLR7 prevents or ameliorates disease in other lupus models." (PMID 35477763, 2022). "Our anti-TLR7 mAb findings suggested that TLR7 drives lupus-associated increases in patrolling monocytes in NZBWF1 mice." (PMID 34868046, 2021). "Since TLR7 and IFNα are intimately linked to lupus pathogenesis, we next wanted to expand on prior results in the 2,6,10,14-tetramethylpentadecane (TMPD, also known as pristane) elicited murine model of lupus." (PMID 33444326, 2021).